BIRC5 (baculoviral IAP repeat containing 5)
Diseases named in the same sentence as BIRC5 in open-access papers (continued):
Sharing a sentence is not in itself a finding about the gene and the disease.
cancer (continued). "This indicates that BIRC5 may be a promising target for cancer therapy." (PMID 29190974, 2017). "With regard to the fact that BIRC5 is expressed at the embryonic stage but its expression is absent in normal adult tissues, changes in the copy number of this gene can possibly be effective in development and progression of cancer by preventing apoptosis in cells." (PMID 27372966, 2016). "In this regard, BIRC5 may have the potential to be considered as a therapeutic target in cancer." (PMID 27372966, 2016). "Furthermore, the overexpression of mtTFA enhances the growth of cancer cell lines, whereas the downregulation of mtTFA inhibits the growth of these cells by regulating mtTFA target genes, such as baculoviral IAP repeat-containing 5 (BIRC5; also known as survivin) and BCL2L." (PMID 26307971, 2015). "For other genes, the proportion changes in different cell types expressing BIRC5, CDK1, AURKA, E2F1, and KIF2C are remarkably similar to the overall proportion changes in different cell types during cancer progression." (PMID 39859485, 2025). "In this study, we designed a self-assembling RNA nanoparticle targeting three oncogenes-hTERT, BIRC5, and FGFR1-key drivers of cancer progression." (PMID 41594586, 2025). "Several genes regulated by HCQ in Ca9-22 cells have been identified as potential cancer therapy targets, including TNFRSF11B, CASP6, BIRC2, and BIRC5." (PMID 41303490, 2025). "Previous research has highlighted the pivotal role of BIRC5 in HCC and its potential for targeted cancer treatment." (PMID 40471223, 2025). "In the cancer pathway, five genes (WNT1, DLL, TRAF1, GST, and GADD45) were upregulated, while CASP3, IKBKA, STAT5A, RPS6KA5, BIRC5, BIRC2/3, and SKP2 were downregulated." (PMID 40723320, 2025). "The results showed that TPX2 and BIRC5 were upregulated, while AGER, TEK, CLIC5, MAMDC2, EMCN, and SEMA3G were mostly downregulated in multiple cancer types." (PMID 40535574, 2025). "Moreover, considering that the presence of autoantibody against BIRC5 likely reflects the immune response targeting BIRC5 antigen, it is suggested that BIRC5 autoantibody-positive cancers with a poor prognosis may exhibit a higher likelihood of favorable responses to immune checkpoint inhibitors." (PMID 38832035, 2024). "For instance, BIRC5 was upregulated in DAB2IP-low Luminal A tumors, and its expression has been proposed to drive the progression of breast and other cancers." (PMID 39418101, 2024). "As per the QPCR array data, Rapamycin is believed to induce apoptosis in cancer cells by altering the components of the extrinsic (CD40LG, DAPK1, LTA, TNFRSF21) and intrinsic (BIRC5, BNIP3) apoptotic pathways as well as the TP73 upstream modulator." (PMID 38276004, 2024). "Of note, patients with upregulated expression of Birc5 and higher level of MDSC infiltration exhibited worse clinical outcomes in HCC and other cancers such as KIRC, LUAD, and SARC." (PMID 37326143, 2023). "The analysis revealed that several members of the IAP family, including NAIP, BIRC2, BIRC3, XIAP, BIRC5, BIRC6, and BIRC7, exhibited higher expression levels in multiple cancers, including HCC." (PMID 37781078, 2023). "STAT3 also plays an important role in cancer cell survival, including PEL cells, by regulating the expression of molecules such as BIRC5." (PMID 37511362, 2023). "We performed a correlation analysis in tumor tissue samples across 33 cancer types, which showed that the correlation coefficient between UBE2C and BIRC5 was 0.23–0.94." (PMID 37958642, 2023). "Baculoviral IAP repeat containing 5 (BIRC5), which is also referred to as survivin, has been extensively studied in different cancer types, including in NSCLC." (PMID 37509650, 2023). "For example, the AURKA inhibitor MLN8237, the BIRC5 inhibitor YM155 and the MELK kinase inhibitor OTS167 have been tested in clinical trials for different types of cancers, and a TTK kinase inhibitor has also shown anti-cancer activity." (PMID 36612203, 2022).
cancer (continued). "Other known and possibly yet undiscovered cancer mechanisms are captured by the SKY92, including cell cycle pathways (BIRC5, TOP2A, and CENPE), cell growth and proliferation (FGFR3), DNA repair (FANCF, FANCI, POLQ), and transcription factor (STAT1)." (PMID 34448362, 2022). "Then, we validated them by molecular docking analysis with some cancer-related PTM-sites (phosphorylation, succinylation, and ubiquitination) of the four top-ranked key proteins EGFR, AURKB, BIRC5, and TOP2A." (PMID 36567949, 2022). "Further investigation of BIRC5, H2AFZ, HIST1H2BK, KIF15, UBE2S, and FBXO5 is crucial to broaden the understanding of cancer invasion and migration, and to promote the discovery and evaluation of new therapeutic targets." (PMID 35406376, 2022). "Given that BIRC5 is highly expressed in LGG, we examined the prognostic value of BIRC5 expression in this cancer type." (PMID 35309512, 2022). "These drug molecules also showed significant binding performance with some cancer-related PTM-sites (phosphorylation, succinylation, and ubiquitination) of top-ranked four key proteins (EGFR, AURKB, BIRC5, and TOP2A)." (PMID 36567949, 2022). "BC2059 has been shown to inhibit β-catenin activation of several cancer genes, such as AXIN2 and BIRC5, with minimal effects on the maintenance of normal tissue functions." (PMID 36240209, 2022). "The cancer genes are composed of genes that code for HER2 (HER2 and GRB7), oestrogen genes (ER, PGR, BCL2, and SCUBE2), proliferation genes (MKI67, STK15, BIRC5, CCNB1, and MYBL2), and invasion genes (MMP11 and CTSL2) as well as GSTM1, CD68, and BAG1." (PMID 36042999, 2022). "Then, to finalize the genes and protein products in question, we evaluated the crucial genes in the GEPIA database and finally confirmed MYLK, SOCS3, STAT5B, BIRC5, PLK1, and RAPGAP1 proteins significantly in this cancer database." (PMID 35928368, 2022). "Baculoviral IAP repeat containing 5 (BIRC5) is overexpressed and plays as a key regulator in the progression of various human carcinomas." (PMID 35461228, 2022). "BIRC5, a member of the inhibitor of apoptosis (IAP) gene family, promotes cancer development by inhibiting the apoptosis of HCC cells, promoting cell proliferation, enhancing chemoradiotherapy resistance and inducing stromal angiogenesis in the tumor." (PMID 34095224, 2021). "In contrast to the relatively known roles of BIRC5, CENPF, and STMMN1 in malignancies, functions of APOC2 and HNRNPC genes in cancer cell are less well defined." (PMID 33828156, 2021). "BIRC5 is a EMT related gene which prevents cell apoptotic through different approaches and participates in cell cycle regulation, and also in cancer cells it regulates autophagy directly." (PMID 35237298, 2021). "As shown, these survival genes (BIRC5, MCL1, XIAP) were significantly increased expressions in the cancer tissues, while the apoptotic gene (CAS9) was reduced compared to the normal tissues from healthy individuals." (PMID 34307149, 2021). "For example, in our work, the pan-cancer TS269 promoter was obtained by fusion of strong cancer promoters of the TERT and BIRC5 genes." (PMID 33804861, 2021). "Further, graph centrality measures suggested the importance of upregulated genes such as BIRC5, UBE2C, BUB1B, KIF20A and PTH1R in cancer." (PMID 34728699, 2021). "This chromosomal region contains several genes connected to cancers including EME1, BRCA1, ERBB2, NF1, RAD51C, BRIP1, BIRC5 and PPM1D." (PMID 34885154, 2021). "Apart from BIRC5, GMIP, IFI16, and TCIRG1, other genes didn’t show significant differences in individual cancer stages." (PMID 35237298, 2021). "Recently it has been demonstrated that PZ-6-QN, a BIRC5-SMAC interaction disruptor, showed promising anti-cancer activity." (PMID 33917186, 2021).
cancer (continued). "Only AURKA, BIRC5, and PLAUR were served as the chemotherapy targets for cancer treatment currently." (PMID 33892811, 2021). "Following RARβ silencing, the down-regulation of cancer-related genes, ALDH1A1, CYP24A1, BIRC5, EDN1, IL-1β and PTGS2 in A549 parental cell suggest the importance of RARβ in controlling the expression of genes related to carcinogenicity." (PMID 33995625, 2021). "Because STAT3 regulates genes that promote cancer cell survival, proliferation, and invasion, we next tested mRNA expression changes of previously established STAT3 target genes, BCL2L1, BIRC5, CCND1, and MMP9 after short-term Olaparib exposure." (PMID 34956861, 2021). "On the other hand, the silencing of RARβ enhanced the expression of BIRC5 in A549 CD166+EpCAM+ and A549 CD166-EpCAM-, suggesting that depletion of RARβ promotes the cancer cell growth via activation of the anti-apoptosis gene." (PMID 33995625, 2021). "BIRC5 was the most overexpressed IAP across multiple tumors, consistent with previous studies showing its strong oncogenic roles across multiple cancers." (PMID 31964418, 2020). "Using the Genomics of Drug Sensitivity in Cancer (GDSC) database for drug sensitivity and gene expression, we identified 8 drugs targeting the apoptosis pathway involving targets of BCL-2, BIRC5, Procaspases, RIPK1, TRAIL, and XIAP." (PMID 31964418, 2020). "Baculoviral IAP repeat containing 5 (BIRC5) is at the crossroads of diverse cancer signaling networks and is a well‐known cancer treatment target." (PMID 32841536, 2020). "Analysis from CHAT revealed that BIRC5, E2F2, KIF2C, FOXM1, and MCM5 were mainly involved in sustaining proliferative signaling in cancer development, with npmi values of 0.15, 0.222, 0.168, 0.218, and 0.157, respectively." (PMID 31579605, 2019). "In this direction, efforts were made to develop a rapid, label-free immunosensor assay using SPR technique to detect BIRC5 protein and discriminate dogs with CMT from healthy and non-cancerous disease counterparts." (PMID 31530877, 2019). "Besides the cell division-associated genes like CCNB2 and BUB1B, we also found genes such as TPX2, BIRC5, TOP2A, SPAG5 and HMGB1, were among the top 10 highly expressed genes in the cell subset, which were reported to be directly or indirectly associated with cancer invasion." (PMID 31888172, 2019). "Several other proteins such as AURKA, AURKB, CHEK1, BIRC5, CDC25B decreases their local PageRanks in cancer which means they become more controlled." (PMID 29370181, 2018). "Some targets of miR-218, such as ROBO1, RICTOR, BIRC5 and LAMB3, have been reported to participate in many cancer signaling pathways, such as the ERK/MAPK, Wnt/β-catenin, and Notch pathways." (PMID 29717030, 2018). "We surveyed a TBX5-mediated gene network and found that it comprised up-regulated expression of baculoviral IAP repeat containing 5 (BIRC5), a member of the inhibitor of apoptosis (IAP) family that plays crucial anti-apoptotic roles in cancer." (PMID 28978111, 2017). "Upregulation of multiple members of gene networks involved in cell cycle, DNA repair, and cancer was observed, including upregulation of BRCA1 and 2, and BIRC5 (Survivin) genes." (PMID 25632947, 2015). "Although the roles for BIRC5 and OCT4 in cancers are well-recognized in a number of previous studies, we gave the first evidence that OCT4 indirectly manipulates the expression and function of BIRC5, and also directly upregulates the expression of CCND1." (PMID 23433354, 2013). "In the blank control group, cancer cells were positive for OCT4 and BIRC5 expression, and few tumor cells were positive for TUNEL staining." (PMID 23433354, 2013). "In the spleen, 8/84 cancer-related genes were affected in FLT mice compared to AEM controls (P<0.05; up: Cdkn2a; down: Birc5, Casp8, Ctnnb1, Map2k1, Mdm2, NFkB1, Pdgfa)." (PMID 24069384, 2013).
cancer (continued). "In the in vitro experiments, silencing of BIRC5 expression effectively induced apoptosis and cell cycle arrest in HCC cells, thereby inhibiting cancer cell proliferation and decreasing cancer cell viability." (PMID 23433354, 2013). "A subset of the targets (BCL2, CLU, HSPB1, BIRC5, EIF4E and RRM2) is being investigated for cancers in combination with approved cytotoxic drugs." (PMID 22989709, 2012). "Survivin also called baculoviral inhibitor of apoptosis repeat-containing 5 (BIRC5) is a member of the inhibitor of apoptosis (IAP) family, which is one of the most cancer-specific proteins identified to date, being unregulated in almost all human tumors." (PMID 22457815, 2012). "• Exertion of anticancer effects through 3 major pathways: apoptosis (BIRC3, BIRC5, caspase-8, caspase-9, and PARP1), transcriptional dysregulation in cancer (CDKN1A, CDKN1B, MMP9, MYC, JUN, and RELA), and cancer progression (caspase-3, CCND1, CTNNB1, VEGFA, and Wnt-1)." (PMID 39181121, 2025). "There is a key biomarker target BIRC5 (survivin) for curcumin that is selected from the human transcriptional regulatory network (HTRN) by the random walk-based graph embedding method to calculate the diffusion profiles of drugs and cancers." (PMID 39026169, 2024). "In DOX-surviving proliferative cells, we found positively correlated gene pairs, for example, two senescent markers (GDF15 and CDKN1A R= 0.54) and anticorrelated gene pairs, for example, GDF15 and genes involved in cancer progression: CDC20 (R= -0.26) and BIRC5 (R= -0.17)." (PMID 39405604, 2024). "We analyzed RNA sequencing expression data of 9736 tumors and 8587 normal samples from The Cancer Genome Atlas (TCGA) and the Genotype-Tissue Expression (GTEx) projects for the expression profiles of centrosome clustering proteins KIFC1, AURKB, BIRC5, and CDCA8." (PMID 39335162, 2024). "Our analyses of TCGA and GTex tumor data and matched normal samples from TCGA and GTex datasets using the Gene Expression Profiling Interactive Analysis (GEPIA) tool showed that KIFC1, AURKB, BIRC5, and CDCA8 are all significantly overexpressed in many different cancer types." (PMID 39335162, 2024). "We evaluated the potential of BIRC5 to distinguish between cancerous and non-cancerous tissues across multiple cancer types using receiver operating characteristic (ROC) curves and area under the curve (AUC) values." (PMID 39703228, 2024). "BIRC5 represents one of 40 genes to be expressed at elevated levels in all cancer tissues but not in normal cells." (PMID 36771042, 2023). "In addition, gene network analysis regarding to mass-type ER-positive cancers showed that ESR1, BIRC5, CAV1, FGFR1, IL6, MIR27, and PTTG1 were upregulated." (PMID 37391754, 2023). "In addition, BIRC5 gene knockdown in LUAD cell lines was proven to significantly inhibit the activity and proliferation of cancer cells." (PMID 37741993, 2023). "In addition to 33 direct YAP targets (such as BIRC5, CDH4, TEAD1) previously established in epithelial and cancer cells, 1,027 genes were newly identified to be YAP signatures in neutrophils." (PMID 36921037, 2023). "Based on these findings, the ceRNA axes involving OIP5-AS1/hsa-miR-204-5p/BIRC5, DCP1A/hsa-miR-204-5p/BIRC5, and PPP1R9B/hsa-miR-204-5p/BIRC5 appear to play a crucial role in the progression of HCC, suggesting potential avenues for targeted therapeutic interventions in this type of cancer." (PMID 38283837, 2023). "The baculoviral inhibitor of apoptosis protein repeat-containing 5 (BIRC5), also known as survivin, is a member of the inhibitor of apoptosis protein (IAP) family and also a target for cancer therapy which exists at the crossroads of many cancer cell signaling networks." (PMID 35909589, 2022). "The CNVs of RAB7A, BIRC5, SERPINE1, and FABP4 were relatively high in most cancers." (PMID 36518255, 2022). "Not just TNBC patients but practically all other cancer types exhibit considerable expression of BIRC5." (PMID 36358602, 2022).
cancer (continued). "For example, ASPM, ECT2, AURKA, BIRC5, CENPF, and EZH2 are amplified in several cancers." (PMID 36612203, 2022). "Our results showed that BIRC5 was up-regulated, whereas FABP4 was down-regulated in most cancers." (PMID 36518255, 2022). "Although genetic alterations in BIRC5 were not common in cancer, BIRC5 expression was significantly higher in cancer tissue compared to normal tissue in the 16 different cancer types." (PMID 35331169, 2022). "For example, shepherdin disrupts the binding of BIRC5 to HSP90, resulting in anti-cancer activity." (PMID 33917186, 2021). "Additionally, the average expression of the proliferating cancer marker genes, MKI167 and BIRC5, was significantly enriched in C4." (PMID 34900703, 2021). "BIRC5 and XRCC2 regulate antiapoptosis and DNA repair, contributing to cancer chemoresistance." (PMID 34154613, 2021). "The three clusters generated contained genes or proteins involved in apoptosis (BIRC3, BIRC5, PARP1, CASP8, and CASP9), transcriptional dysregulation in cancer (CDKN1B, RELA, CDKN1A, MYC, JUN, and MMP9), and cancer progression (CCND1, CASP3, CTNNB1, WNT1, and VEGFA) pathways." (PMID 34836311, 2021). "Although BIRC5 is an intracellular protein and therefore not a good target for CAR-T therapies, BIRC5-peptide mediated immunotherapy has been shown to exhibit low toxicity in clinical trial and can increase BIRC5 peptide-specific CTLs that kill cancer cells." (PMID 34638823, 2021). "In recent years, several studies have reported the role of BIRC5 in cancer, but the role of BIRC5 in pan-cancer or its impact on the immune microenvironment has not been investigated." (PMID 33431968, 2021). "In accordance with these recent data, we found in this study that genetic depletion of Fasn resulted in the lower growth rate of c-Myc/MCL1/Cre tumors as well as in the decrease of Cdk1, Cdk2, Skp2, and Survivin/Birc5 genes, which have been previously found to be regulated by FASN in cancer cells." (PMID 33187130, 2020). "Furthermore, correlations between the two PDEIRGs (BIRC5 and LPA) and immune checkpoints of cancer treatment (such as CTLA4, PD-1, and PD-L1) were demonstrated." (PMID 33195412, 2020). "In HCT-15 cells, reduced transcription of cell cycle mediating genes (CCND1, PCNA, CDK2, CDKN1B), and reduced transcription of anti-apoptotic genes (BMI1, BIRC5 and BCL2), support a cancer suppressive and favorable FOXO3/FOXM1 ratio upon combined TNKSi/MEKi treatment." (PMID 30717152, 2019). "The levels of BIRC5/Survivin, expressed in most human cancers, but absent in normal tissues, and shown to promote proliferation and inhibition of apoptosis of cancer cells including BC, were also significantly reduced by DLL1 downregulation (2-fold)." (PMID 31107884, 2019). "BIRC5 and GADD45B are involved in apoptosis, one of the most important hallmarks of cancer." (PMID 29304754, 2018). "Furthermore, AREG affected downstream molecules like BIRC5, CCNA2, CCNB2, TOP2A, MMP9, MMP1, CXCR4, have roles in development and progression of various types of cancers." (PMID 30517191, 2018). "Survivin (BIRC5) is an oncogene that imparts increased growth and resistance to apoptosis and is expressed selectively in cancers and undifferentiated cells but not normal tissues." (PMID 28350329, 2017). "BIRC5 is an effective drug target for cancer therapy due to its high expression in tumors, but not in normal tissues." (PMID 29212257, 2017). "Contrary to our expectation, TERT and Survivin/BIRC5, which are highly expressed in various cancer cells, appeared not suitable as marker genes of immortalized RPE cells." (PMID 28811571, 2017).